IGF1R (insulin like growth factor 1 receptor)
Diseases named in the same sentence as IGF1R in open-access papers (continued):
Sharing a sentence is not in itself a finding about the gene and the disease.
polycystic ovary syndrome (2 papers, 2020 to 2021). A disorder that manifests as multiple cysts on the ovaries. "Insulin plays a central role in polycystic ovary syndrome, and it engages with the insulin-like growth factor 1 receptor to enhance steroid production in ovaries and adrenal glands." (PMID 34088325, 2021).
prostate adenocarcinoma (2 papers, 2022 to 2025). "UM tumors displayed the third highest IGF-1R gene expression amongst cancer types, surpassed only by prostate adenocarcinoma (PRAD) and breast invasive carcinoma (BRCA)." (PMID 36551732, 2022). "The presence of IGF1R-SPINT1 in patients with prostate adenocarcinoma, which we detected in patient 8, has not been previously reported." (PMID 39847581, 2025).
retinal degeneration (2 papers, 2018 to 2022). Degeneration of the retina. "We determined that conditional deletion of IGF-1R in photoreceptors and pan-retinal cells produces age-related visual function loss and retinal degeneration." (PMID 35840554, 2022). "Thus, targeting neuroinflammation through the IGF-1/IGF-1R system and/or additional pharmacological strategies might conduct the regression of retinal degeneration and represents a challenging therapeutic strategy." (PMID 30026694, 2018).
salivary carcinoma (2 papers, 2019). "In fact, the significant delay in salivary carcinoma onset induced by parental #20 cell vaccine was lost with both IGF1R-expressing cell vaccines." (PMID 30979001, 2019). "We previously found that rhabdomyosarcomas, but not salivary gland carcinomas, overexpressed IGF2 concomitant to membrane IGF1R, thus suggesting that, like the human counterpart, experimental rhabdomyosarcoma could harbor an autocrine IGF circuit." (PMID 30732578, 2019).
schwannoma (2 papers, 2014 to 2021). A benign, usually encapsulated slow growing tumor composed of Schwann cells. "The most effective combinations in Schwann cells were slightly different and included: ALK-IN-1/dasatinib, TAE226 (a dual FAK/IGF-1R inhibitor)/dasatinib, and dasatinib/simvastatin (an HMG-CoA reductase inhibitor) for schwannoma." (PMID 34264955, 2021).
selenium deficiency (2 papers, 2019 to 2020). A nutritional deficiency disease resulting from inadequate selenium levels in the body, which can lead to impaired function of selenoproteins essential for antioxidant defense and thyroid hormone metabolism. "Previous studies have reported that IGF1R played a positive role in weight gain and bone growth and development in broilers, and selenium deficiency in broilers could inactivate the IGF-1R/PI3K/Akt/mTOR pathway, reduce the growth rate of the spleen and the number of splenic lymphocytes." (PMID 32609751, 2020).
Sepsis (2 papers, 2015 to 2025). Sepsis is defined as life-threatening organ dysfunction caused by a dysregulated host response to infection. "We identified significant colocalization evidence for MCOLN1 (mucolipin 1) and IGF1R in relation to sepsis in critical care, with posterior probability of colocalization (PPH4) values of 0.705 and 0.732, respectively." (PMID 40761792, 2025). "Notably, upregulation of ADCK1, IGF1R, and MAP3K1 at the transcriptional level was found to predict higher sepsis risk, while increased expression of BLK and KCNJ15 correlated with lower risk." (PMID 40761792, 2025). "As would be predicted from an IGF-1R inhibitor, there was a higher incidence of hyperglyecemia (three grade 3 and one grade 4) in arm B vs. none in arm A. There was one toxicity-related death in arm A after complications of chemotherapy due to sepsis." (PMID 26793618, 2015). "Moreover, IGF1R and MCOLN1, supported by MReQTL, SMR, and colocalization evidence, exhibited strong binding affinities for chlorogenic acid, which is widely recognized for its anti-inflammatory effects in sepsis." (PMID 40761792, 2025).
SHORT syndrome (2 papers, 2020 to 2021). A rare disorder characterized by multiple congenital anomalies, including short stature, hyperextensibility of joints, ocular depression, Rieger anomaly and teething delay in which the cause of the disease is a mutation in PIK3R1 gene. "We diagnosed the genetic causes of patients 5, 6, and 7 as IGF1R abnormality, SHORT syndrome, and Floating-Harbor syndrome, respectively." (PMID 32546215, 2020). "Mutations in PIK3R are associated with the SHORT syndrome which is characterized by IUGR, and mutations causing dysregulation of IGF1R can also result in IUGR." (PMID 33682876, 2021). "IGF1R abnormality, SHORT syndrome, and Floating-Harbor syndrome are differential diagnoses of SRS because of the shared phenotypes among these syndromes and SRS." (PMID 32546215, 2020). "Patients 5, 6, and 7 had genetically diagnosed IGF1R abnormality, SHORT syndrome, and Floating-Harbor syndrome, respectively, which have phenotypic overlap with SRS." (PMID 32546215, 2020). "Furthermore, our data confirmed IGF1R abnormality, SHORT syndrome, and Floating-Harbor syndrome are differential diagnoses of SRS because of the shared phenotypes among these syndromes and SRS." (PMID 32546215, 2020).
thrombosis (2 papers, 2017 to 2022). "Furthermore, inhibition of IGF-1R abolished the protection conferred by miR-223 deficiency on thrombosis." (PMID 28487522, 2017).
Thymic epithelial tumors (2 papers, 2014 to 2019). "Thymic epithelial tumors express insulin-like growth factor-1 receptor (IGF-1R), particularly recurrent or advanced tumors and those with aggressive histological subtypes." (PMID 24847446, 2014).
thymic tumors (2 papers, 2013 to 2023). "Though several signaling pathways have been explored in thymic tumors, clinical trials with EGFR, KIT, VEGF, and IGF-1R, histone deacetylase, DNA methyltransferase, tropomyosin receptor kinase A, and, cyclin-dependent kinase inhibitors documented only modest clinical responses in advanced disease." (PMID 23765114, 2013).
thyroid (2 papers, 2022 to 2023). "It is commonly assumed that thyroid autoantibodies cause TED by eliciting a cross-reactive reaction against the thyrotropin receptor (TSHR) and the IGF-1R on ocular fibroblasts." (PMID 37884559, 2023).
Tremor (2 papers, 2014 to 2019). An unintentional, oscillating to-and-fro muscle movement about a joint axis. "In females, tremor onset was delayed in heterozygous Igf-1r HD mice (HD; Igf-1r+/−) when compared to controls (HD; Igf-1r+/+ mice) (p = 0.002)." (PMID 25140802, 2014). "The chosen time point criteria was dictated by the age of onset of tremors in the HD; Igf-1r+/+ group of females, which was around 13.5 weeks of age." (PMID 25140802, 2014). "Furthermore, a recent study showed that intercrossing heterozygous insulin like-growth factor receptor 1 (Igf-1r) knockout mice, which have been reported to be long-lived, with female N171-82Q HD mice delayed tremor onset in this HD model." (PMID 31695068, 2019). "For instance, this decrease in inclusion numbers, observed at 13 weeks of age, coincides with the delay in tremor onset seen in HD; Igf-1r+/− females, although it has no discernible effect on survival or other motor phenotypes assessed in HD mice." (PMID 25140802, 2014).
uterine serous carcinoma (2 papers, 2013 to 2017). "Finally, BRCA1 was also shown to inhibit IGF1R expression in uterine serous carcinoma cells." (PMID 28706506, 2017).
vascular dementia (2 papers, 2023 to 2024). A degenerative vascular disorder affecting the brain. "To expand our search for a regulatory mechanism for vascular dementia, we chose two miRNAs (miR-145-5p and miR-122-5p) and one lncRNA (IGF1R) published in research." (PMID 38384571, 2024).
visceral leishmaniasis (2 papers, 2018 to 2022). A severe form of leishmaniasis characterized by irregular bouts of fever, substantial weight loss, swelling of the spleen and liver, and anemia (which may be serious). "Similarly, the insulin-like growth factor 1 receptor (IGF1R) has previously been shown to be involved in arginase (Arg1) expression in visceral leishmaniasis and also targeted by rotaviruses, dsRNA viruses, to manipulate the PI3K/Akt pathway and block autophagy." (PMID 35992159, 2022).
acute leukemia (1 paper, 2015). A clonal (malignant) hematopoietic disorder with an acute onset, affecting the bone marrow and the peripheral blood. "In acute leukemia patients, no studies with reagents exclusively targeting IGF1-R have been conducted." (PMID 26450156, 2015).
adrenocortical malignant tumor (1 paper, 2014). "In addition, gene amplification of other loci was identified in this adrenocortical malignant tumor, but no IGF1R copy number variation was evidenced in the remaining cases." (PMID 25110710, 2014).
age-related macular degeneration (1 paper, 2024). Age-related loss of vision in the central portion of the retina (macula), secondary to retinal degeneration. "IGF-1 is produced in the retinal pigment epithelium (RPE), and in age-related macular degeneration (AMD), there is an increased expression of IGF-1R." (PMID 38300646, 2024). "Contrastingly, in neovascular age-related macular degeneration (AMD), there is an overexpression of both IGF-1 and IGF-1R in RPE." (PMID 38300646, 2024).
airway hyperresponsiveness (1 paper, 2018). "Igf1r-deficient mice exhibit no airway hyperresponsiveness, and a selective decrease in blood and BALF eosinophils, lung IL-13 levels, collagen, and smooth muscle, as well as a significant depletion of goblet cell metaplasia and mucus secretion markers after home dust mite exposure." (PMID 30018981, 2018).
alcohol (1 paper, 2025). "Chronic alcohol reduced IL Igf1r and CA1 Igf1 transcript levels in males as well as CA1 Igf1r transcript levels in females." (PMID 41400881, 2025). "In males, chronic alcohol reduced Igf1r transcript levels in the IL, but not PL or CA1." (PMID 41400881, 2025).
alcoholic cardiomyopathy (1 paper, 2009). A dilated cardiomyopathy which is associated with consumption of large amounts of alcohol over a period of years. "A decreased activation of cardiomyocyte IGF-1R by IGF-1 has been reported in a model of alcoholic cardiomyopathy and this was associated with an absence of protein synthesis after IGF-1 incubation." (PMID 19818143, 2009).
alcoholic cirrhosis (1 paper, 2009). "But in patients with alcoholic cirrhosis, hyperinsulinaemia decreases IGFBP3 concentrations, resulting in increased IGF1 bioactivity, which stimulates insulin-like growth factor 1 receptor IGF1R activity in mammary tissue cells." (PMID 22493645, 2009).
alcoholic hepatitis (1 paper, 2014). Acute hepatitis resulting from ingestion of alcohol. "In adjacent noncancerous liver, IGF-1R was strongly expressed in only one patient with alcoholic hepatitis." (PMID 25052889, 2014).
amyloidosis (1 paper, 2025). A disorder characterized by the localized or diffuse accumulation of amyloid protein in various anatomic sites. "Studies in mouse models have shown that reduced IGF-1 signaling via Igf1r haploinsufficiency reduces disease burden in models of amyloidosis." (PMID 41402425, 2025).
anaplastic large cell lymphoma (1 paper, 2015). Anaplastic large cell lymphoma (ALCL) is a rare and aggressive peripheral T-cell non-Hodgkin lymphoma, belonging to the group of CD30-positive lymphoproliferative disorders, which affects lymph nodes and extranodal sites. "Likewise, recent data have shown that IGF1R tyrosine kinase and the NPM-ALK oncogene associate and reciprocally increase their phosphorylation and activation to induce survival of T-cell ALK-positive anaplastic large-cell lymphoma cells." (PMID 26445453, 2015).
and neck cancer (1 paper, 2024). "and neck cancer (HNC), the invasion-associated molecules LAMA3, LAMC2, THBS1, IGF1R, PDGFB, and transforming growth factor β1 can serve as prognostic indicators or molecular therapeutic targets to improve the survival rates of HNC." (PMID 38877482, 2024).
anthrax (1 paper, 2025). "How EF and LF exert opposing effects on MEK and PI3K signaling, and through what integrated mechanism EGFR and IGF1R transactivation contribute to anthrax pathogenesis, will require further investigation." (PMID 41158867, 2025).
aortic aneurysm (1 paper, 2025). A ruptured aneurysm located in the wall of the proximal portion of the descending aorta proceeding from the arch of the aorta. "Meanwhile, a recent study reported that administration of IGF1R antagonists protects against aortic aneurysm in rodent and porcine models, suggesting the pathogenic role of IGF1R signaling in aortopathy." (PMID 39817456, 2025).
Aortic dissection (1 paper, 2023). Aortic dissection refers to a tear in the intimal layer of the aorta causing a separation between the intima and the medial layers of the aorta. "A recent study identified IGF1R as a critical gene in aortic dissection." (PMID 36835806, 2023).
basal cell carcinoma (1 paper, 2021). A carcinoma involving the basal cells. "While the molecular pathway such as IL-12, basal cell carcinoma, estrogen receptor, Ephrin A, PIK3, CD8, CD4 and IGF1R were significantly inhibited." (PMID 34493740, 2021).
benign meningioma (1 paper, 2013). A grade I, slowly growing meningioma. "A recent study showed that inhibitors of IGF1R may have anti-tumoral effects in benign meningioma." (PMID 23840654, 2013).
bipolar disorder (1 paper, 2026). A disorder of the brain that causes unusual shifts in mood, energy, activity levels and the ability to carry out day-to-day tasks. "IGF1R was associated with bipolar disorder (BD) risk in blood-specific analyses." (PMID 41750613, 2026).
bone metabolism disorders (1 paper, 2020). "Further studies on the miR‐7025‐5p/IGF1R axis may provide novel insights into understanding the pathogenesis of bone metabolism disorders, revealing new therapeutic targets." (PMID 31755174, 2020).
Brain atrophy (1 paper, 2021). Partial or complete wasting (loss) of brain tissue that was once present. "While we did not detect any effects on cortical insulin or insulin-like growth factor 1 receptor m-RNA levels, LRGT significantly reduced brain atrophy in the db/db and APP/PS1xdb/db mice." (PMID 34975451, 2021).
brain hemorrhage (1 paper, 2020). "Indeed, one study showed that the presence of Igf1, the ligand for Igf1r, resulted in improved BBB integrity following brain hemorrhage." (PMID 32843537, 2020).
bronchioalveolar carcinoma (1 paper, 2011). "Both primary and metastatic bronchioalveolar carcinoma cell lines H358 and H1650 showed a moderate activation of the HER1 and HER2 pathways, with H358 also exhibited a moderate activation of the c-MET and IGF-1R pathways." (PMID 22091388, 2011).
cartilage tumours (1 paper, 2016). "By immunohistochemistry, IGF1R expression levels were determined in tissue microarrays of 187 cartilage tumours and ten paraffin embedded cell lines." (PMID 27418340, 2016).
central precocious puberty (1 paper, 2018). "Since members of the IGF family are involved in the onset of puberty, we aimed to identify polymorphisms in insulin (INS), IGF-1, IGF-2, IGF-1 receptor (IGF1R), IGR2R, and IGF binding protein 3 (IGFBP-3) that may alter the risk for development of central precocious puberty." (PMID 30249230, 2018).
cervical adenocarcinoma (1 paper, 2020). An adenocarcinoma arising from the cervical epithelium. "Interestingly, a report indicates that miR‐223 suppresses cell proliferation by targeting IGF‐1R in HeLa cells, which models cervical adenocarcinoma." (PMID 32491253, 2020).
Charcot-Marie-Tooth disease (1 paper, 2023). An inherited degenerative disorder involving the peripheral nerves. "The alternatively spliced isoform Kif1bβ has been more extensively studied; it transports synaptic vesicle precursors through IGF1R, regulates axonal outgrowth, and is implicated in Charcot-Marie-Tooth disease and neuroblastoma." (PMID 37296096, 2023).
cholangiomas (1 paper, 2025). "Therefore, the cholangiomas we observed could originate from cholangiocytes lacking PTEN/IR/IGF1R expression in our models." (PMID 40115165, 2025).
chronic lung disease (1 paper, 2021). According to the definitions of the American and British Thoracic Societies, including pulmonary functional tests, X-rays, and CT scans for items such as fibrosis, bronchiectasis, bullae, emphysema, nodular or lymphomatous abnormalities. "For example, acute and chronic lung diseases are associated with an upregulation of IGF1 and IGF1-R." (PMID 34831169, 2021).
dengue (1 paper, 2024). "Thus, the activity of ERBB2 and IGF1R during DENV infection should be further investigated to understand their utility as dual targets of dengue therapeutics." (PMID 38585651, 2024). "We observed that EPHB3, ERBB2, FGFR2, IGF1R, and RET are upstream regulators both of kinases shown to be important in previous dengue research and of kinases predicted by KiR." (PMID 38585651, 2024).
diabetic eye disease (1 paper, 2025). A group of disorders affecting the eye in patients with diabetes mellitus. "For example, one study demonstrated that transgenic mice overexpressing IGF1R exhibited retinal changes similar to those seen in human diabetic eye disease, including vascular alterations and neovascularization, even under normal glucose and insulin levels." (PMID 40391004, 2025).
diabetic ketoacidosis (1 paper, 2016). The metabolic condition resulted from uncontrolled diabetes mellitus, in which the shift of acid-base status of the body toward the acid side because of loss of base or retention of acids other than carbonic acid is accompanied by the accumulation of ketone bodies in body tissues and fluids. "Previous research suggests the IR and Igf-1r can compensate for one another since mice lacking both receptors specifically in β-cells died from diabetic ketoacidosis within 4-8 weeks." (PMID 27384998, 2016).
disc degeneration (1 paper, 2021). "A higher disc-narrowing score on radiographs was associated with the presence of the G allele (GG or GC genotype) in the insulin-like growth factor-1 receptor; genetic variation at the IGF1R gene locus caused disc degeneration." (PMID 33494410, 2021).
dissection (1 paper, 2021). The separation and isolation of tissues for surgical purposes, or for the analysis or study of their structures. "At first, although it has been shown that E2F2, IGF1R, and BDNF can cause arterial-related diseases, there is no research to prove the relationship between aortic dissection and these target gene." (PMID 34620091, 2021).
Down syndrome (1 paper, 2024). "We believe that the therapeutic potential of IGF-1/IGF-1R signaling remains very promising and should be further explored, as for example, in Down's syndrome." (PMID 39638246, 2024).
ductal carcinoma (1 paper, 2009). "Also, expression of oncoproteins with anti-apoptotic activities, including receptor tyrosine kinase ErbB2, colony-stimulating factor 1 receptor, SRC, and IGF1R, has been shown to elicit abnormal, filled phenotypes that resemble human ductal carcinoma in vivo." (PMID 20043854, 2009).
dysplasia (1 paper, 2025). A usually neoplastic transformation of the cell, associated with altered architectural tissue patterns. "Frequency: It has been demonstrated that there is an increased pIRS1 staining (IGF1R activation marker) in 43.2% of BE patients and 70% of EAC patients, a phenomenon that implies the significant effect of IGF1R in BE progression towards dysplasia and EAC." (PMID 41369383, 2025).